BRCA1 (BRCA1 DNA repair associated)
Diseases named in the same sentence as BRCA1 in open-access papers (continued):
Sharing a sentence is not in itself a finding about the gene and the disease.
breast cancer (continued). "Understanding these mechanisms will be valuable for identifying new biomarkers and therapeutic targets and strategies for BRCA1-associated breast cancer." (PMID 27043663, 2016). "The Breast Cancer susceptibility gene 1 (BRCA1) is the most commonly mutated gene in familial breast cancer cases and is strongly associated with both the TN subtype and basal-like breast tumours." (PMID 27463681, 2016). "Although caused by genes involved in homologous DNA repair, breast cancers caused by BRCA1 and BRCA2 mutations appear to be rather different diseases." (PMID 27087880, 2016). "Because younger women diagnosed with breast cancer and those with a family history of breast and/or ovarian cancer are at higher risk of carrying a BRCA1/2 gene mutation, diagnostic DNA testing is offered to this subset of breast cancer patients." (PMID 26833044, 2016). "As denosumab has been approved for use in humans, the drug is immediately available to test its efficacy on breast cancer prevention in BRCA1-mutation carriers in clinical trials." (PMID 27881737, 2016). "Breast cancer patients with family histories of ovarian cancer exhibited the highest overall mutation rate of BRCA1 and BRCA2, which implied that BRCA1 and BRCA2 mutations are more likely to occur in families with a history of both breast and ovarian cancer." (PMID 26852015, 2016). "In support of this notion, we found that both RAD51 and BARD1, a component of the BRCA1 breast cancer susceptibility HDR protein complex, readily accumulate at telomeres in Rap1−/− MEFs expressing TRF2ΔB and in WT MEFs expressing TRF2ΔB; L286R." (PMID 26941064, 2016). "A familial predisposition exists in 5–10 % of all breast cancer cases, of which 15–20 % is due to germline mutations in the BRCA1/2 genes." (PMID 26748927, 2016). "Olaparib is approved for BRCA-mutated ovarian cancer patients and Phase III testing is in progress for breast cancer patients with BRCA1/2 mutations." (PMID 27556570, 2016). "On the other hand, our data shows that germline BRCA1 mutations have a limited contribution to the pathogenesis of male breast cancer, which is in accordance with the literature." (PMID 27532258, 2016). "The breast cancer susceptibility associated with BRCA1/2 deficiencies has been recapitulated in mouse models carrying the respective gene deletions." (PMID 27037238, 2016). "The birth year‐dependent onset of breast cancer (BC) in BRCA1/2 mutation carriers suggests a risk‐modifying role for reproductive and life style factors." (PMID 27066510, 2016). "This study aims to provide evidence for a clinically meaningful improvement of the experimental regimen over standard of care chemotherapy for metastatic BRCA1- or BRCA2-mutated breast cancer." (PMID 27323902, 2016). "To test these ideas biochemically, we probed the enzymatic accessibility of the SCD region of wild type and mutated BRCA1 contained in the nuclear fractions of breast cancer cell lines." (PMID 27583302, 2016). "It is well known that breast cancer women with BRCA1/2 mutation have a high risk of developing contralateral breast cancer." (PMID 27129401, 2016). "Hereditary breast cancers arising from mutation of the tumour suppressor gene, BRCA1, closely resemble sporadic TNBC/BLBCs while BRCA1 expression is downregulated in up to 30% of sporadic BLBCs." (PMID 26943587, 2016). "Prophylactic salpingo-oophorectomy in women with BRCA1 mutations decreases breast cancer risk by 50%, or more if the oophorectomy is performed before the age of 40." (PMID 27246982, 2016). "It is well known that germ-line and somatic pathogenic mutations in the tumor suppressor genes, BRCA1 and BRCA2 (BRCA1/2), confer increased risk for ovarian and breast cancers." (PMID 27769273, 2016).
breast cancer (continued). "BRCA1 mutation or depletion correlates with basal-like phenotype and poor prognosis in breast cancer but the underlying reason remains elusive." (PMID 27043660, 2016). "A high frequency of germline and somatic BRCA1/2 P/LP variants was detected in unselected Chinese breast cancer patients." (PMID 27257965, 2016). "BRCA1 dysregulation and/or mutation are closely associated with a higher risk of breast cancer in familial cases." (PMID 27043660, 2016). "Mutations in the breast cancer susceptibility gene BRCA1 significantly increase the risk of developing breast cancer." (PMID 27043663, 2016). "Impact of BRCA1/2 P/LP variants on the DFS of breast cancer patients from subgroups of stage 0~II and III." (PMID 27257965, 2016). "The main aim of this study was to screen the male patients with breast cancer for BRCA1 and BRCA2 mutations as well as the status of tissue tumor markers including ER, PR, HER-2 and basal marker (CK5/6)." (PMID 27478808, 2016). "Since it became evident that only 15%-20% of the familial risk for BC/OC can be explained by mutations in the major breast cancer-susceptibility genes BRCA1 and BRCA2, the search for additional BC/OC susceptibility loci has been pursued." (PMID 27504877, 2016). "In the present study, TOP1 was detected at an increased level in the BRCA1-deficient secretome and exosome-like vesicles as well as in human BRCA1-related breast carcinomas." (PMID 27566577, 2016). "Chang and colleagues also reported a null association with all‐cause death in a cohort of BC patients in the Breast Cancer Family Registry in Northern California, USA when excluding those with BRCA1 and BRCA2 mutation." (PMID 26799372, 2016). "AICAR showed biological activity in human cells by selective inhibition of growth of BRCA1-deficient HCC1937 breast carcinoma cells, BRCA1-deficient BCR-ABL1-positive leukemia cells, and BRCA2-deficient Capan-1 pancreatic adenocarcinoma cells." (PMID 27649245, 2016). "Among them were several nuclear proteins, which have previously been identified in BRCA1-deficient breast carcinomas (TOP1, SMC3, SSRP1 and DHX9)." (PMID 27566577, 2016). "Although there are controversies, chemotherapeutic effectiveness of PARP1 inhibitors have been assessed in BRCA-deficient breast carcinomas and ovarian carcinomas with a BRCA1/2 mutation." (PMID 27643881, 2016). "TOP1 expression was independently associated with BRCA1/2-related breast carcinomas (adjusted odds ratio [OR] 3.75; 95% confidence interval [95% CI], 1.82–7.71, p < 0.001)." (PMID 27566577, 2016). "Women who have inherited mutations in BRCA1 or BRCA2 are at greatly increased risk of developing breast cancer (BC) and ovarian cancer (OC)." (PMID 27836010, 2016). "Two earlier published reviews also addressed the association between BRCA1/2 carriership and breast cancer survival." (PMID 25816289, 2015). "A woman’s risk for breast cancer increases to 45% to 65% by age 70 if she carries a mutation in either the BRCA1 or BRCA2 gene (Centers for Disease Control and Prevention [CDC], 2014; Chen & Parmigiani, 2007; NCI, 2015)." (PMID 26557407, 2015). "The prevalence of BRCA1 mutation in familial or early-onset breast cancer led more and more studies to concentrate on the role of BRCA1 in TNBC." (PMID 25695063, 2015).
breast cancer (continued). "Nevertheless, the breast cancer patient gene expression microarray and methylated DNA immunoprecipitation analyses clearly show that BRCA1 mutation is significantly associated with FOXA1 gene promoter methylation and expression downregulation." (PMID 25531315, 2015). "The major breast cancer susceptibility genes, BRCA1 and BRCA2, play a role in the homologous recombination pathway (HR) for repairing the double strand breaks (DSB) in DNA3." (PMID 26108708, 2015). "Recently, additional common alleles have been reported to be associated with increased breast cancer risk for BRCA1 and BRCA2 mutation carriers in large retrospective studies." (PMID 25339628, 2015). "At this time, more long term data are needed to understand the impact of oophorectomy on breast cancer incidence in BRCA1/2 mutation carriers." (PMID 26870808, 2015). "The objective of the current study was to describe trends over the years 1995–2009 in the timing of genetic testing and of prophylactic mastectomy in breast cancer patients carrying a BRCA1/2 mutation." (PMID 25700605, 2015). "Despite significant findings of cancer-driving mutations in the BRCA1 gene, estrogen receptor (ER)-positive breast cancers progress upon treatment with DNA damaging-cytotoxic therapies." (PMID 28536406, 2015). "Breast cancer susceptibility gene 1 (BRCA1) is the first tumour suppressor gene identified in familial breast cancer." (PMID 25880076, 2015). "Germ-line inactivating mutations in the breast cancer susceptibility gene BRCA1 (OMIM#113705) confer a marked hereditary predisposition to breast and ovarian cancer (HBOC)." (PMID 25884417, 2015). "We evaluated 200 Bulgarian women with primary invasive breast cancer and with personal/ family history of breast cancer for the presence of unequivocally damaging germline mutations in BRCA1/2 using Sanger sequencing." (PMID 26183948, 2015). "PARP inhibitors are considered promising anti-cancer agents and currently being tested in clinical trials in hereditary breast cancer patients harboring mutations in BRCA1 and BRCA2 genes." (PMID 25975349, 2015). "Collectively, these results demonstrate that BRCA1 enhances miR-143 and miR-145 processing of human breast cancer-associated specific miRNAs in vivo." (PMID 25961039, 2015). "BRCA1 p.Q356R is an example of a variant that has a frequency of minor allele over 5% and an increased odds ratio for breast cancer over 1.5 in carriers." (PMID 26485759, 2015). "Ingenuity Pathway Analysis (IPA) confirmed that multiple pathways were modulated by Gem, and that ISRIB enhanced Gem-mediated expression of genes implicated in BRCA1's DNA damage response and hereditary breast cancer signaling." (PMID 26469962, 2015). "Breast cancers diagnosed in patients carrying a BRCA1 germline mutation display distinct histo-pathological as well as molecular characteristics and have been observed to differ from sporadic cases also regarding chemotherapeutic sensitivity." (PMID 26029931, 2015). "In conclusion, this study shows that 1H HRMAS MRS can distinguish between docetaxel sensitive and resistant BRCA1-mutated mouse mammary tumors because they are metabolically distinct." (PMID 25890200, 2015). "A small number of studies of Ukrainian women breast cancer patients have revealed the presence of a founder mutation in BRCA1, 5382insC." (PMID 26468334, 2015). "Multiple studies have revealed various miRNAs that specifically target the three missing receptors ER, PR, and HER2 as well as the breast cancer susceptibility gene BRCA1 in TNBC development." (PMID 26633365, 2015).
breast cancer (continued). "Using the best-evidence synthesis, we concluded that there is still indecisive evidence for an association between BRCA1 mutation carriership and unadjusted/adjusted overall survival of breast cancer patients." (PMID 25816289, 2015). "BRCA1 is a well-established breast cancer susceptibility gene, and is involved in maintaining genome integrity through pathways including participation in DNA damage repair, the control of cell cycle checkpoints and apoptosis." (PMID 25789047, 2015). "Once diagnosed with unilateral breast cancer, BRCA1/2 mutation carriers have a 16–55 % risk of developing contralateral breast cancer within 25 years, depending on, among other factors, age at first diagnosis and the mutated gene." (PMID 25700605, 2015). "In principle, we have confirmed the reported association between the presence of variant SNPs and early onset of breast cancer in BRCA1 mutation carriers." (PMID 26052370, 2015). "A study of 564 French Canadian women with breast cancer under 50 years of age reported a 4.8% carrier frequency in a mutation screen for eight BRCA1/BRCA2 mutations found to recur in French Canadian HBC/HBOC cancer families." (PMID 25925845, 2015). "A body of experimental and clinical evidence indicates that BRCA1 levels influence the susceptibility of women to develop breast cancer as well as the aggressiveness of the tumors." (PMID 25762631, 2015). "We performed a mutation analysis in the 184 BRCA1 TR genes, using the complete catalog of somatic mutations obtained from the whole-genome sequencing of 21 breast cancers, a subset of which (n = 5) were BRCA1 mutant." (PMID 25699710, 2015). "Female BRCA1 or BRCA2 gene mutation carriers have an increased risk of developing breast cancer of 27–88 %, and a maximum lifetime risk of developing ovarian cancer of 6–59 %." (PMID 25700605, 2015). "Earlier, similar associations with other genes were also found in breast cancer patients also carrying germline mutations in BRCA1/2 genes." (PMID 25591549, 2015). "Together BRCA1 and BRCA2 mutations account for about 20–25% of all inherited breast cancers, and BRCA1/2-mutation carriers face a high risk of developing breast cancer." (PMID 25531315, 2015). "We decided not to participate in the initial studies of these modifiers of breast cancer penetrance, and we now have one of the few sufficiently large series of well-described BRCA1 mutation carriers to validate the findings reported by others." (PMID 26052370, 2015). "It has been reported that breast cancers in BRCA1 mutation carriers frequently have a distinctive basal-like phenotype." (PMID 25961039, 2015). "This variant has been reported as being associated with decreased BRCA1 expression, increased breast cancer risk, and greater likelihood of having stage IV breast cancer." (PMID 26630397, 2015). "They demonstrated that, breast cancer cells containing germ line mutations in BRCA1 and BRCA 2 genes become sensitized to PARP inhibitors in a PARP1 dependant manner and lose sensitivity to PARP inhibition on regaining BRCA2 functionality." (PMID 25606064, 2015). "There is a strong correlation between the presence of mutations in the BRCA1/2 gene and morphology of the breast cancer." (PMID 25705321, 2015). "Early studies identified a very low proportion of somatically acquired BRCA1 inactivating mutations in sporadic breast cancer." (PMID 25884417, 2015). "(2002) revealed a 96% risk reduction in ovarian cancer and a 53% risk reduction in breast cancer in 551 women with a BRCA1 or BRCA2 mutation." (PMID 26557407, 2015). "For breast cancer patients with BRCA1 mutation, single-agent cisplatin neoadjuvant therapy can achieve an extremely high pCR rate of 83%." (PMID 26267318, 2015). "While all women face formidable challenges posed by the threat of living with or at increased risk for breast cancer, those of Ashkenazi Jewish descent face additional challenges owing to higher BRCA1/2 mutation prevalence in this population." (PMID 27417765, 2015).
breast cancer (continued). "It is further estimated that about 5%–10% of all breast cancer cases are attributable to a BRCA1/2 mutation, and women identified with a BRCA1/2 mutation face significantly increased lifetime risks of developing breast cancer." (PMID 27417765, 2015). "Another possible weakness of our study is the usage of external estimates of breast cancer and OvC relative risks to BRCA1 and BRCA2 mutation carriers." (PMID 26025000, 2015). "Screening programs for cancer susceptibility genes is exemplified by screening of BRCA1/2 in families of breast cancer." (PMID 25908947, 2015). "In order to evaluate which BRCA1 polymorphisms or mutations characterize female breast cancer in Argentina, the current study enrolled 206 females with breast cancer from several hospitals from the southeast of Argentina." (PMID 25624909, 2015). "Today, the prevention of breast cancer among BRCA1 and BRCA2 mutation carriers has focused on surgical options such as risk-reducing bilateral mastectomy and bilateral salpingo-oophorectomy." (PMID 26496879, 2015). "Second, the associations between breast cancer risk and rs3803662 polymorphism were considered with respect to ER status and BRCA1/2 mutation carriers." (PMID 26239137, 2015). "Approximately 5% to 10% of breast cancer cases and 11% to 18% of ovarian cancer cases are a result of a mutation in the BRCA1 and BRCA2 genes, known as hereditary breast and ovarian cancer (HBOC)." (PMID 26557407, 2015). "Strikingly, the sensitivity of mammography in diagnosing breast cancer is lower in BRCA1 mutation carriers compared to BRCA2 mutation carriers or women with a moderate to high familial breast cancer risk." (PMID 26000714, 2015). "Previous studies showed that breast cancer has an inherited component, and the high-penetrance breast cancer predisposing genes, BRCA1 and BRCA2, account for up to 10–40 % of inherited breast cancer." (PMID 26489409, 2015). "The participants who had previously had genetic testing and genetic counselling and been found to carry a BRCA1/2 mutation recalled receiving risk estimates for breast cancer and OC described as a percentage risk." (PMID 25391615, 2015). "The BRCA1 mutation c.5266dupC (also known as 5382insC or 5385insC) was detected in a sample of 193 breast cancer patients in Ukraine by multiplex mutagenically separated PCR using published specific primers." (PMID 26468334, 2015). "Approximately 5–10% of breast cancers and 10% of ovarian cancers have a hereditary component, which in most cases is associated with clinically significant mutations in the BRCA1 and BRCA2 genes." (PMID 25948282, 2015). "Here we present the results of a screening for the frequency of the BRCA1 mutations 5382insC among 193 Ukrainian breast cancer patients." (PMID 26468334, 2015). "Only 5–10 % of breast cancer cases is linked to germline mutations in the BRCA-1 gene and occurs early in life." (PMID 26715507, 2015). "In a recent prospective analysis, contralateral RRM was found to be associated with improved overall survival in BRCA1 or BRCA2 mutation carriers with a prior primary breast cancer (PBC)." (PMID 26669313, 2015). "A recent meta-analysis showed that 22% of selected high-risk breast cancer patients with TNBC were carriers of BRCA1 mutations." (PMID 26083025, 2015). "Regarding BRCA1 associated breast cancer cases TRβ positivity turned out to be a positive prognostic factor for five-year (p = 0.007) and overall survival (p = 0.026) while TRα positivity predicted reduced five-year survival (p = 0.030)." (PMID 26029931, 2015). "In the meta-analysis, the strength of relationships of BRCA1 promoter methylation with breast cancer risk and its clinicopathological features were systematically investigated." (PMID 26643130, 2015). "Germline mutations in BRCA1 predispose women to breast and ovarian cancers, with a 50–85 % lifetime risk of developing breast cancer." (PMID 25986046, 2015).